INS (insulin)
Diseases named in the same sentence as INS in open-access papers (continued):
Sharing a sentence is not in itself a finding about the gene and the disease.
diabetes (continued). "This is because it is proposed that caffeine impacts blood glucose concentrations in individuals with existing diabetes, by inhibiting glucose uptake into muscle cells, even in the presence of insulin." (PMID 34200398, 2021). "When we had a change and had to go into the insulin, when we mutually decided on that, he informed me how that was the better management tool for the diabetes at that point." (PMID 34690778, 2021). "These diseases cause hyperketonemia for a variety of reasons, including poor insulin signaling in diabetes, impaired fatty acid metabolism in heart failure (HF), and slow ketone body elimination as a result of genetic disorders." (PMID 34631141, 2021). "This study suggests that glucose homeostasis in muscles can be suggested as an important strategy for diabetes therapy and can improve insulin sensitivity and reduce postprandial hyperglycemia." (PMID 33628395, 2021). "Individuals with T2DM, constituting about 90% of all cases of diabetes, are unable to properly use their insulin supply due to insulin resistance." (PMID 34489478, 2021). "This study is a local adaptation of the DUNE study (The Diabetes Unmet Need with basal insulin Evaluation)." (PMID 33532606, 2021). "Following an initial diagnosis of diabetes, participants were given behavioural advice and most took oral medication or insulin to manage their diabetes." (PMID 34294059, 2021). "Known risk factors for hypoglycemia in pregnancy are the duration of type 1 diabetes mellitus, history of previous severe hypoglycemia, hypoglycemia unawareness, changes in insulin treatment, and HbA1c < 6.5% (48 mmol/mol)." (PMID 34959363, 2021). "There are some medicinal plants believed to treat diabetes, and scientific studies have reported certain medicinal plants do contain antidiabetic properties, such as improved insulin sensitivity and hypoglycemic activities." (PMID 34691218, 2021). "These can cause reduced insulin secretion, leading to the development of different forms of diabetes, or increased insulin secretion (hyperinsulinism)." (PMID 33828531, 2021). "Dipeptidyl peptidase-4 inhibitors (DPP-4i) provide a unique antihyperglycemic effect by regulating incretin peptides in type 2 diabetes mellitus (T2DM) patients who are inadequately controlled with insulin therapy." (PMID 34446063, 2021). "One patient with type 2 diabetes mellitus was taking insulin, while two patients with persistent impaired glucose tolerance were receiving metformin." (PMID 34063446, 2021). "Diabetes is due to either the failure of pancreatic β cells to make enough insulin (type 1) or the cells that express insulin receptors fail to respond to insulin (type 2; type 2 diabetes (T2D))." (PMID 34210954, 2021). "The common complication of diabetes is hypoglycemia, which is often related to the use of insulin or strict management of blood glucose." (PMID 34925792, 2021). "There are several factors associated with depression in diabetic patients: comorbidities, diabetes-related complications, body mass index (BMI) ≥ 30 kg/m2, glycated hemoglobin (HbA1c) ≥ 8.0%, smoking, insulin treatment, and a long history of diabetes." (PMID 34745773, 2021). "Lower levels of insulin were observed in the diabetic groups (D and CD) after diabetes induction compared to the control groups (C and CC) (P=0.001)." (PMID 34777519, 2021). "It is not about eating and exercising a lot; it is more about eating balanced and exercising properly, always checking glucose and injecting myself with the insulin my body needs” (male, 15 years, 1 year 3 months with diabetes)." (PMID 33807277, 2021). "Our results indicate that imipramine exacerbates diabetes mellitus complications by reducing serum insulin levels, as evidenced by the fact that chronic imipramine use resulted in a reduced proportion of β-cells in mouse pancreas sections." (PMID 34564583, 2021). "HbA1c, BMI, age, diabetes duration, and insulin requirements were positively correlated with thrombotic biomarkers." (PMID 33730349, 2021).
diabetes (continued). "The gene of SOCS1 was found to be targeted by insulin and aldesleukin, of which both have been applied to treat autoimmune diseases, including systemic lupus erythematosus, type 1 diabetes mellitus, and HIV." (PMID 34872583, 2021). "Secondly, metformin prevented statin-induced worsening of insulin sensitivity in subjects with late-onset hypogonadism and prediabetes, constituting a population particularly prone to the development of diabetes." (PMID 34086261, 2021). "Despite significant advances in T1D management, including intensive insulin therapy and diabetes technologies, achieving the recommended target HbA1c level in youth with T1D remains challenging." (PMID 34272437, 2021). "A previous study also found that the effects of a dipeptidyl peptidase-IV inhibitor on plasma insulin concentrations were different between late- and early-stage models of diabetes." (PMID 33916828, 2021). "In this non-inferiority study, 108 patients with type 1 diabetes were randomly allocated to either an AI-managed group that received insulin treatments using the AI system or a manually managed group that received insulin treatments by a diabetes specialist." (PMID 34902070, 2021). "According to other authors’ research, it is plausible that pregnancy yields immunological tolerance and stimulates endogenous insulin production in women with type 1 diabetes mellitus." (PMID 34959363, 2021). "Currently, diabetes cannot be cured, and the treatment of diabetes consists of handling hyperglycemia by providing an exogenous insulin and medications supply or by islet cell transplantation." (PMID 34987478, 2021). "GDF-8 inhibition in skeletal muscle improves dyslipidemia and insulin sensitivity thereby preventing the development of diabetes in lipodystrophy mouse model." (PMID 33874963, 2021). "Taken together these results suggest that overexpression of PIns1 in APCs is able to partially dampen immune responses against insulin and reduce diabetes incidence in NOD mice." (PMID 33841427, 2021). "Recent studies have shown that some PPARG agonists retain insulin sensitization with few side effects and are widely used in the treatment of type 2 diabetes mellitus; ESR includes ESR1 and ESR2, and most of the effects of oestrogen are mediated by ESR1." (PMID 34164430, 2021). "The past decade revealed that cell identity changes, such as dedifferentiation or transdifferentiation, accompany the insulin-producing β-cell decay in most diabetes conditions." (PMID 33918250, 2021). "We have tried to recapitulate the sequence of events to assess the glucose sensitivity and insulin signaling in-vitro to gain further insights into the beneficial effect of P-MSCs in the management of pre-clinical diabetes." (PMID 34417511, 2021). "Then, we decided to use MaAsLin2 to verify the multivariable association between clinical metadata, such as sex, age, BMI, diabetes duration in years, total daily insulin, daily carbs, and HbA1c in a linear model." (PMID 33445500, 2021). "Most of the published papers on insulin pump treatment with a CGM system focus on clinical parameters to evaluate metabolic control of diabetes." (PMID 34070638, 2021). "The most commonly used diabetes drug was insulin (62.06%), followed by metformin (34.40%), α-glucosidase inhibitor (21.28%), and sulfonylureas (20.57%)." (PMID 34513785, 2021). "Of persons with diabetes, 15.8% had insulin treatment, 37% had oral hypoglycemic medication, and 25.8% received only dietary treatment, suggesting that at least over 70% of these participants had type 2 diabetes." (PMID 34583686, 2021). "Type 1 diabetes mellitus (T1DM) is an autoimmune disease characterized by the destruction of pancreatic islet β-cells leading to inadequate insulin synthesis." (PMID 34906241, 2021). "The matched groups were comparable regarding the prevalence of diabetes mellitus and insulin therapy." (PMID 34140595, 2021).
diabetes (continued). "The diabetes stage, with two variables dependency on medication or insulin injection and comorbidity, had the largest contribution to clinical outcomes HbA1c level." (PMID 34461877, 2021). "In Tanzania, where current and prior undernutrition is common, more attention needs to be paid to insulin production in the clinical management of diabetes." (PMID 33740034, 2021). "Prior studies in humans have described associations of different mtDNA mutations with elevated fasting insulin, glucose, and HOMA-IR values, as well as associations with type 2 diabetes and maternally inherited forms of diabetes." (PMID 34370595, 2021). "About 11–47% of patients with CS develop diabetes mellitus, mainly due to decreased insulin sensitivity and impairment of beta-cell function induced by GC excess." (PMID 33025384, 2021). "All forms of diabetes have in common the ultimate dysfunction of the pancreatic beta cells and the consequent inadequate circulating insulin levels." (PMID 33828531, 2021). "Glucagon-like peptide-1 receptor agonists (GLP-1 RAs) are a class of medications utilized for the treatment of diabetes mellitus by mechanisms promoting incretin release and insulin production." (PMID 34336446, 2021). "More importantly, modern studies have shown that Astragalus polysaccharide can effectively reduce blood glucose levels, improve insulin sensitivity, inhibit the apoptosis of pancreatic β cells, and play a key role in treating diabetes complications." (PMID 35002950, 2021). "The number of drugs used to control diabetes (oral hypoglycemic and insulin) also reduced post-surgery." (PMID 33859902, 2021). "Diabetes is a chronic metabolic disease condition characterized by heightened levels of glucose in the blood as a result of either decreased insulin secretion or the development of insulin resistance." (PMID 35194439, 2021). "Diabetes is characterized by a failure of functional β‐cells to adapt insulin secretion to compensate for increasing insulin resistance, driving diabetes development." (PMID 34542937, 2021). "T1D+DS patients developed diabetes earlier and achieved better metabolic control with a lower insulin dose than T1D controls." (PMID 33939908, 2021). "Ablation of Pdia4 alleviated diabetes as shown by reduced islet destruction, blood glucose and HbA1c, reactive oxygen species (ROS), and increased insulin secretion in diabetic mice." (PMID 34542937, 2021). "Current treatment of diabetes depends on multiple daily injections of exogenous insulin to continuously regulate blood glucose levels." (PMID 34641460, 2021). "Evidence suggests that insulin therapy of patients with type 2 diabetes mellitus (T2DM) is frequently discontinued." (PMID 33402226, 2021). "One is insulin (INS), a hydrophilic peptide for diabetes treatment, and another one is cyclosporine A (CysA), a hydrophobic peptide for psoriasis treatment." (PMID 34959402, 2021). "Patients with a low insulin daily dose and optimal glycaemic control after two years from diabetes onset were also investigated for monogenic diabetes, regardless of their autoimmunity status and/or C-peptide levels." (PMID 34496959, 2021). "Numerous studies have shown that microneedles can be used for transdermal delivery of metformin, lidocaine, insulin, vaccines, human growth hormone (hGH) and nanoparticles (NP) in the treatment of wounds (acne), diabetes therapy, tumors and so on." (PMID 34641460, 2021). "At her second pregnancy, at period of amenorrhea (POA) of 6 weeks, diabetes was identified, and she was started on insulin." (PMID 34238353, 2021). "Further understanding the neurocognitive effects of transient insulin deprivation, as highlighted in this study, will have important clinical implications, given the growing number of people with diabetes and use of insulin pumps across the world." (PMID 33561011, 2021).
diabetes (continued). "Out-of-pocket payment for health services by patients greatly limit their ability to purchase insulin and test strips for their diabetes management." (PMID 34104298, 2021). "Additional evidence of decreased hepatic insulin sensitivity and poor response to agonists of PPARs in adiponectin-deficient mice suggests that adiponectin can slow the progression of diabetes by directly affecting insulin sensitivity." (PMID 34906241, 2021). "Nanotechnology in diabetes studies has encouraged the development of new modalities for measuring glucose and supplying insulin that hold the potential to improve the quality of life of diabetics." (PMID 34683861, 2021). "Coupled with the further discovery that the transport of insulin into the brain is reduced with diabetes and in patients with cognitive dysfunction led to the recognition of brain as a new target organ for insulin." (PMID 35058808, 2021). "Certain aspects of the Hajj pilgrimage (e.g., travel, hot weather, outdoor religious activities, and variable accessibility to cool storage conditions) make optimal storage of insulin challenging for pilgrims with diabetes." (PMID 34136581, 2021). "Treatment of older insulin-treated diabetes patients is particularly challenging because of their comorbidities, including cardiovascular and kidney disease, cognitive decline, and orthopedic problems causing impaired mobility." (PMID 34077674, 2021). "Increased insulin sensitivity can improve the condition and control the blood sugar level better, resulting in a lower likelihood of diabetes." (PMID 33663083, 2021). "Insulin replacement therapy and medications that increase insulin secretion and improve insulin sensitivity are the main therapies used to treat diabetes." (PMID 34882233, 2021). "East African Diabetes Study Group Guidelines recommend insulin storage in a clean container in a cupboard at room temperature." (PMID 33855206, 2021). "Proof-of-principle studies have shown that islet transplantation can lead to independence from exogenous insulin in people with diabetes." (PMID 33996792, 2021). "Increasing age, usually above 45 years, is a major risk factor for T2DM, and menopause also disturbs glucose homeostasis and insulin sensitivity, further elevating diabetes risks." (PMID 34577625, 2021). "In an HF diet/low-dose STZ (HFD/STZ) rat model of diabetes, oral doses of A. platensis (250, 500 or 750 mg/kg body weight) for 30 days were shown to ameliorate levels of fasting blood glucose, insulin, and hepatic enzymes." (PMID 33572056, 2021). "A decrease of insulin content and insulin signaling in the brain is characteristic of Alzheimer’s and Parkinson’s diseases and diabetes mellitus." (PMID 34769198, 2021). "Diabetes mellitus (DM) is a disease characterized by elevated plasma glucose levels due to a deficit in insulin production, a failure in its action, or a mixture of both." (PMID 34356251, 2021). "The use of the toolbox has been discussed in three applicative examples, which range from synthetic demo to a real application in diabetes research where Visual4DTracker played a key role to quantitatively analyse insulin granules dynamic in living beta-cells." (PMID 33557754, 2021). "YouTube videos educate patients about medication, healthy diets, the use of inhalers, exercise plans, and methods to inject insulin to control diabetes." (PMID 33949965, 2021). "Clinical experience indicates that many individuals with longstanding insulin-treated diabetes have impaired hypoglycemia awareness." (PMID 33919723, 2021). "Insulin treatment partially counteracted the damages induced by diabetes on BMC, BMD and cortical thickness and tenacity." (PMID 34440530, 2021). "Some cross-sectional and longitudinal studies have been conducted between SED, PA, and diabetes-related markers, including glucose, insulin, and homeostasis model assessment of insulin resistance (HOMA-IR)." (PMID 34200736, 2021).
diabetes (continued). "Diabetes is characterized by chronic hyperglycemia and inflammatory diseases due to insulin resistance and dysfunction of insulin production." (PMID 34096884, 2021). "We previously found that SRSF6 regulated AS of many genes involved in central β-cell functions, such as insulin secretion, evidencing its role as key splicing regulator for β-cells and thus suggesting a link to diabetes." (PMID 33376132, 2021). "The endocrinologists and diabetes clinic nurses at [name of hospital] were very aggressive in pushing for treatment with insulin and actually played down some of the risks/dangers associated with insulin usage." (PMID 33858469, 2021). "To validate this critical concept, we performed long-term islet transplantations (an experimental treatment for insulin insufficient diabetes mellitus) with sex-matched and sex-mismatched islets in ICR mice." (PMID 34571259, 2021). "Both insulin injections and carbohydrate intake have an important influence in blood glucose levels for type 1 diabetes mellitus (T1DM) patients." (PMID 34450712, 2021). "An inducible L-IDE-KO model of study would also help elucidate the impact of IDE function on insulin sensitivity and glucose homeostasis before and after the onset of diabetes in mouse models of T2DM such as the db/db." (PMID 33477364, 2021). "C-peptide detection is often used in the classification and diagnosis of diabetes, and C-peptide can truly reflect the actual insulin level, so the body produces as much insulin as it synthesizes." (PMID 34427289, 2021). "The characteristics of the diabetic Asian population included increased visceral obesity, impaired insulin secretion, reduced pancreatic β-cell mass, young age of diabetes onset, increased microvascular complications, and ischemic stroke." (PMID 34457016, 2021). "Enhancement of insulin levels and/or insulin sensitivity is at the epicenter of diabetes management." (PMID 35058808, 2021). "Diabetes mellitus (DM) is a chronic metabolic disorder characterized by long-lasting hyperglycemia, which mainly occurs due to disturbances in insulin action, insulin secretion, or both." (PMID 33685505, 2021). "For example, participants of diabetes simulations often acknowledged the challenge of needing privacy for insulin self-injection." (PMID 34863312, 2021). "Ketoacidosis is a common reason for the discovery of diabetes in children and results in a subclinical cerebral edema that progresses (even in the first hours of insulin therapy) to encephalopathy." (PMID 34309858, 2021). "Only two patients were taking metformin and/or another oral diabetes medication, however, this was in addition to insulin." (PMID 34001014, 2021). "Hypoglycemia is a common side effect of MSC‐mediated treatment of diabetes, especially in patients using insulin injection." (PMID 33660433, 2021). "The patient was diagnosed type 1 diabetes mellitus with ketoacidosis at age 6 and blood glucose was controlling with insulin four times each day (Insulin Glargine Injection once daily and Insulin Aspart Injection three times a day before each meal)." (PMID 33879153, 2021). "Before insulin was developed as a treatment for hyperglycemia, reducing carbohydrate intake was the main strategy in the management of diabetes." (PMID 33805161, 2021). "Reports have shown that pomegranate consumption results in improved short-term hypoglycemic responses, pancreatic β-cell function, and insulin resistance in individuals with diabetes." (PMID 34959837, 2021). "The ADA standards of medical care in diabetes advocates insulin as a safe option for the management of both T1DM and T2DM in pregnancy, as it does not cross the placenta." (PMID 34071359, 2021). "Type 2 diabetes mellitus (T2DM) is a metabolic syndrome with disorders of glucose, protein, and fat caused by deficiency of insulin secretion and/or insulin function." (PMID 34825006, 2021).